METTL14 (methyltransferase 14, N6-adenosine-methyltransferase non-catalytic subunit)
Diseases named in the same sentence as METTL14 in open-access papers (continued):
Sharing a sentence is not in itself a finding about the gene and the disease.
Ewing sarcoma (2 papers, 2022 to 2024). A small round cell tumor that lacks morphologic, immunohistochemical, and electron microscopic evidence of neuroectodermal differentiation. "Recently, researchers have observed higher levels of METTL3, ALKBH5, METTL14 and IGF2BP1 in chemotherapy-resistant OS cells, and METTL14 and YTHDF2 are associated with multiple drug sensitivity in Ewing's sarcoma." (PMID 38355483, 2024). "The prognostic model constructed using m6A-related genes METTL14 and TYHDF2, can be a potential prognostic biomarker for Ewing’s sarcoma, with the survival rate of cases in the high-risk group being much lower than that of the low-risk group." (PMID 35487915, 2022). "We therefore have reason to believe that METTL14 and YTHDF2 can serve as prognostic biomarkers for Ewing's sarcoma associated with m6A." (PMID 35487915, 2022). "Secondly, we performed cell cultures of Ewing's sarcoma and control cells and the results of the qRT-PCR experiments performed showed that METTL14 expression was higher in both Ewing's sarcoma cell lines than in the control cell lines, with statistically significant differences (P < 0.05)." (PMID 35487915, 2022). "We were able to find from the pictures of the specific staining by immunohistochemistry that the specific expression of both METTL14 and YTHDF2 in Ewing's sarcoma was higher than their respective expression in the control group." (PMID 35487915, 2022). "Immunohistochemical specific staining revealed higher expression of both METTL14 and YTHDF2 in Ewing’s sarcoma than in the paraneoplastic tissues." (PMID 35487915, 2022). "METTL14 and TYHDF2 serve as biomarkers of Ewing's sarcoma, and we can use the expression of these two genes in Ewing's sarcoma to predict the survival risk and prognosis of Ewing's sarcoma patients, providing new and useful information to guide clinical diagnosis and treatment." (PMID 35487915, 2022).
glomerulosclerosis (2 papers, 2022 to 2025). A hardening of the kidney glomerulus caused by scarring of the blood vessels. "Clinically, this METTL14/Sirt1 axis exacerbates proteinuria and glomerulosclerosis, positioning METTL14 modulation as a therapeutic strategy." (PMID 40895041, 2025). "However, another study revealed that podocyte-specific METTL14 deletion upregulated Sirt1 expression, thereby alleviating apoptosis and inflammation, regulating autophagy, and delaying the development of proteinuria and glomerulosclerosis." (PMID 36157472, 2022).
heart failure (2 papers, 2022 to 2025). Inability of the heart to pump blood at an adequate rate to meet tissue metabolic requirements. "Knockdown of METTL14 demonstrated a decrease in expression of heart failure markers Anp, Bnp, and β-Mhc mRNA." (PMID 36351918, 2022). "Furthermore, downregulation of METTL14 alleviated cardiac fibrosis during I/R remodeling, as evidenced by Masson trichrome staining and prevented increased expression of heart failure markers Anp, Bnp, β-Mhc, and α-Sma on mRNA levels." (PMID 36351918, 2022). "Studies to date have shown that METTL14 can be preferentially reduced, relative to METTL3, in a variety of cellular contexts and have profound effects on cell development, cancer, and late-stage heart failure." (PMID 40266881, 2025).
ischemic cardiomyopathy (2 papers, 2024 to 2025). Ischemic cardiomyopathy is a cardiomyopathy in which a weakness in the muscle of the heart due to inadequate oxygen delivery to the myocardium with coronary artery disease being the most common cause. "Moreover, to further explore the relationship between EFEMP1 and METTL14, we comprehensively analyzed multiple public datasets, including patients with ischemic cardiomyopathy (GSE263297) and young and aged mouse hearts (GSE225576 and GSE289885)." (PMID 40606020, 2025).
keloid (2 papers, 2022 to 2025). An irregularly shaped, elevated mark on the skin caused by deposits of excessive amounts of collagen during wound healing. "Among all m6A regulators, the levels of METTL3 and WTAP were significantly higher in keloid samples, while the levels of ALKBH5, FTO, and METTL14 exhibited little differences." (PMID 40860194, 2025). "But there is no significant change in METTL14, FTO, and ALKBH5 between these two groups (data are not shown), which indicates that the keloid is under a hypermethylated condition." (PMID 36263010, 2022).
lung fibrosis (2 papers, 2023 to 2025). "Regarding m6A writers, the methyltransferases METTL3, METTL14, and ZC3H13 have been identified as potential biomarkers for early diagnosis of pulmonary fibrosis and as prognostic indicators for patients with pulmonary fibrosis." (PMID 39756462, 2025).
lymphoma (2 papers, 2019 to 2025). A malignant (clonal) proliferation of B- lymphocytes or T- lymphocytes which involves the lymph nodes, bone marrow and/or extranodal sites. "In lymphoma, the expression of METTL14 is also considered an important prognostic indicator, which related to the degree of tumor differentiation and patients’ survival rate, with low expression of METTL14 potentially indicating poorer clinical outcomes." (PMID 41323393, 2025).
medulloblastoma (2 papers, 2024). A malignant, invasive embryonal neoplasm arising from the cerebellum. "Knockdown of key m6A writer genes METTL3 and METTL14 in a group 3 medulloblastoma cell line (D425-Med) decreased cell proliferation and upregulated many M6LSig genes identified in our in silico analysis, suggesting that the signature genes are functional in medulloblastoma." (PMID 39198884, 2024).
myocardial infarct (2 papers, 2021 to 2026). "The increase in Mettl14 level led to reduced myocardial infarct size in I/R mice compared with the negative control (gene-free empty virus for Mettl14, Adv-Null)–treated hearts post-I/R." (PMID 35004673, 2021).
ocular melanoma (2 papers, 2024 to 2025). A melanoma that arises from the structures of the eye or ocular adnexa. "Notably, this study definitively establishes the pro-cancer role of METTL14 in CM, despite the ongoing controversy surrounding its function in ocular melanoma." (PMID 41316357, 2025). "Some studies suggest that METTL14 may act as a tumor suppressor in ocular melanoma, highlighting the complexities and unresolved questions surrounding m6A regulation." (PMID 41316357, 2025).
osteonecrosis (2 papers, 2021 to 2023). A none disease characterized by death of bone tissue due to a lack of blood supply. "By regulating the expression of key genes, METTL14 also has been reported to have functional roles in some diseases, such as steroid-associated osteonecrosis." (PMID 36795489, 2023). "Interestingly, the m6A methyltransferase METTL14 was obviously down-regulated in osteonecrosis tissues and BMSCs from SONFH patients, while the demethylase ALKBH5 was up-regulated in SONFH tissues, but not in SONFH BMSCs." (PMID 34910686, 2021).
ovarian tumor (2 papers, 2022 to 2024). "Further investigation revealed that METTL14 reduced the stability of TROAP mRNA, which consequently arrested ovarian tumor cells at the G1 phase of the cell cycle and inhibited their proliferation." (PMID 35251990, 2022). "Interestingly, we also found that METTL14 and YTHDF2 expression were decreased in ovarian tumor." (PMID 38505602, 2024).
postmenopausal osteoporosis (2 papers, 2021 to 2022). Metabolic disorder associated with fractures of the femoral neck, vertebrae, and distal forearm. "We elucidated the miR‐103‐3p/METTL14/m6a signaling axis in osteoblasts and highlighted the critical roles of this signaling axis in reduced bone mass in postmenopausal osteoporosis." (PMID 33440070, 2021). "In summary, our results illustrate that miR‐103‐3p plays critical roles in postmenopausal osteoporosis by inhibiting osteoblast activity and bone formation and reveal a previously unrecognized signaling axis involving miR‐103‐3p/METTL14/m6A in osteoblasts." (PMID 33440070, 2021).
psoriasis (2 papers, 2023 to 2025). An autoimmune condition characterized by red, well-delineated plaques with silvery scales that are usually on the extensor surfaces and scalp. "In psoriasis, METTL14 interacts with UCA1 to regulate the HIF‐1α/NF‐κB axis, while also modulating the SOCS3/STAT3 pathway to attenuate IL‐6‐mediated inflammation." (PMID 41316520, 2025). "Our findings suggest that lncRNA UCA1 promotes keratinocyte-driven inflammation in psoriasis by targeting and inhibiting METTL14 protein and then activating the HIF-1α/STAT3 and NF-κB signaling pathways." (PMID 37076497, 2023). "Taken together, this work indicates that UCA1 positively regulates keratinocyte-driven inflammation and psoriasis development by binding to METTL14, and activating HIF-1α and NF-κB signaling pathway." (PMID 37076497, 2023). "This suggests that METTL14 may also regulate innate immunity in psoriasis." (PMID 37076497, 2023). "Through its interaction with METTL14, UCA1 activates both HIF‐1α and NF‐κB signaling pathways, consequently promoting keratinocyte‐mediated inflammatory responses and contributing to psoriasis pathogenesis." (PMID 41316520, 2025).
steatosis (2 papers, 2024). Increased lipid within the cytoplasm of cells. "An overexpression of METTL14 induces the m6A modification, resulting in steatosis and hepatic fat accumulation." (PMID 37902450, 2024). "METTL14 expression was lowered in the group of patients with mild, moderate, or severe steatosis compared with patients with minimal or no steatosis." (PMID 38627387, 2024).
abdominal aortic aneurysm (1 paper, 2025). Enlargement and ballooning of the vessel that supplies arterial blood to the abdomen, pelvis and legs. "In further support of our data, others have reported high METTL14 expression in human abdominal aortic aneurysms and dissections and vascular calcification, pathologies associated with significant VSMC dedifferentiation." (PMID 40266881, 2025).
acute pancreatitis (1 paper, 2025). An acute inflammatory process that leads to necrosis of the pancreatic parenchyma. "A recent study reported that METTL14 up-regulation promotes pancreatic cell inflammation and ferroptosis by increasing ACSL4 expression in an N6-methyladenosine-dependent manner in severe acute pancreatitis." (PMID 40785592, 2025).
adenovirus infection (1 paper, 2020). "When we assessed viral genome amplification by qPCR, we detected only a minimal change after knockdown of METTL3 or METTL14, indicating m6A is not required for early stage adenovirus infection." (PMID 33243990, 2020).
alopecia (1 paper, 2020). Hair loss usually from the scalp. "Subsequently, we evaluated the relationship between the clinical symptoms of SLE including LN, NPLE, arthritis, fever, rash, alopecia, ulceration, pleuritis, pericarditis, and the expression of METTL14, ALKBH5, and YTHDF2 in PBMCs." (PMID 32583611, 2020).
Autoimmunity (1 paper, 2024). The occurrence of an immune reaction against the organism's own cells or tissues. "Conditional deletion of Mettl3 or Mettl14 in murine CD4+ T cells impairs T cell differentiation and homeostasis, while mice lacking Mettl3 or Mettl14 specifically in Treg cells displayed severe autoimmunity despite normal numbers of Foxp3+ Treg cells." (PMID 37307819, 2024).
Azoospermia (1 paper, 2025). Absence of any measurable level of sperm,whereby spermatozoa cannot be observed even after centrifugation of the semen pellet. "The frequency of underdeveloped gonads and incomplete germline development phenotypes increased by simultaneous knockdown of Smed-METTL3 and Smed-METTL14 (METTL3;METTL14(RNAi)), resulting in 85 % of the ovaries lacking oocytes and 71 % of samples with azoospermia." (PMID 41322074, 2025).
calcification (1 paper, 2021). Process by which organic tissue becomes hardened by the physiologic deposit of calcium salts. "Interestingly, the forced expression of METTL14 in stressed human artery smooth muscle cells (HASMCs) has the opposite effect, which may predict the therapeutic potential of METTL14 in vascular calcification-involved diseases." (PMID 33431045, 2021).
chronic gastritis (1 paper, 2025). Inflammation of the stomach that is chronic in nature. "The expression levels of METTL14 and VAMP3 in Hp+ chronic gastritis tissues were much lower than those in Hp− chronic gastritis tissues." (PMID 39827141, 2025). "To clarify the correlation between the METTL14/VAMP3 axis and H. pylori-mediated malignant transformation of the gastric mucosa, we first identified the expression of METTL14 and VAMP3 in human Hp− chronic gastritis tissues and Hp+ chronic gastritis tissues." (PMID 39827141, 2025). "Moreover, the expression of METTL14 and VAMP3 in Hp+ chronic gastritis tissues is much lower than that in Hp− chronic gastritis tissues." (PMID 39827141, 2025).
cleft palate (1 paper, 2024). Cleft palate is a fissure type embryopathy that affects the soft and hard palate to varying degrees. "In summary, the level of m6A methylation modification in the palatine process mesenchyme of cleft palate mice was abnormally elevated throughout the key period of palate development, and was positively correlated with the expression of METTL14 (E13.5–E15.5)." (PMID 38674123, 2024). "In conclusion, METTL14 regulates palatal mesenchymal cell proliferation and cycle-related protein expression relies on m6A methylation modification, affecting the occurrence of cleft palate." (PMID 38674123, 2024). "Western blotting found that the protein expression level of m6A methyltransferase METTL14 in the palatine process mesenchyme of embryonic mice with cleft palate (RA10D) was significantly higher than that of the normal palate in the control group during the same period (p < 0.0001)." (PMID 38674123, 2024).
Cognitive impairment (1 paper, 2025). Abnormal cognition is characterized by deficits in thinking, reasoning, or remembering. "In summary, this study revealed that the cognitive impairment caused by Sevo is related to regulation of METTL14/DUSP6 through m6A methylation." (PMID 41175640, 2025).
colon adenocarcinoma (1 paper, 2022). "Based on TCGA pan-cancer correlation analysis, it was demonstrated that ZNRD1-AS1 expression was significantly and positively correlated with METTL3 in all tumor types, with the exception of colon adenocarcinoma, and with METTL14 in all cancer types (R > 0.3), including LUAD and LUSC." (PMID 36581942, 2022).
endometrial adenocarcinoma (1 paper, 2021). "In contrast, the expression of METTL14, KIAA1429, and ZC3H13 was drastically decreased in patients with endometrial adenocarcinoma." (PMID 34149936, 2021). "In our study, the expression of METTL14 and KIAA1429, methylase enzymes promoting methylation of the m6A site, was significantly decreased in endometrial adenocarcinoma." (PMID 34149936, 2021).
Fever (1 paper, 2020). Body temperature elevated above the normal range. "This decreased mRNA expression of METTL14 was associated with WBC and M; this decreased mRNA expression of ALKBH5 was associated with CRP, N%, L%, NLR, C3, and fever; and the decreased mRNA expression of YTHDF2 was associated with L%, NLR, C3, and fever." (PMID 32583611, 2020).
gallbladder cancer (1 paper, 2025). "We proceeded to investigate whether METTL3 and METTL14 regulate the processing of pri‐miR‐146a in gallbladder cancer cells." (PMID 40785027, 2025).
gastritis (1 paper, 2025). Inflammation of the stomach. "Then, we established a gastritis mouse model of H. pylori infection to detect the expression of METTL14 and VAMP3." (PMID 39827141, 2025).
hemangioma (1 paper, 2025). A benign vascular lesion characterized by the formation of capillary-sized or cavernous vascular channels. "RT-qPCR further revealed a marked downregulation of METTL14, an m6A writer protein, during the involuting tissues, while the expression levels of other RNA m6A relative genes had no significantdifferentiation, suggesting that m6A modification may be involved in regulating hemangioma progression." (PMID 40978048, 2025).
Hepatitis (1 paper, 2025). Inflammation of the liver. "In contrast, other m6A regulators, including METTL3, METTL14, WTAP, FTO, ALKBH5, YTHDC1, and YTHDC2, exhibited different protein expression patterns during ConA-induced hepatitis." (PMID 40092485, 2025).
HIV-1 infection (1 paper, 2025). The type species of lentivirus and the etiologic agent of acquired immunodeficiency syndrome (AIDS). "We observed that HIV-1 infection promotes the interaction between METTL3/METTL14." (PMID 41085277, 2025). "Here, we demonstrate that HIV-1 infection of activated primary CD4+ T cells promotes the interaction between the m6A writer complex subunits methyltransferase-like 3 and 14 (METTL3/METTL14)." (PMID 41085277, 2025).
infarct (1 paper, 2021). "We found that Mettl14 protected against cardiac I/R injury as indicated by the reduction in apoptosis, cardiac infarct size, and improvement in cardiac dysfunction." (PMID 35004673, 2021).
Infertility (1 paper, 2024). "Notably, stratified analysis demonstrated that carriers of rs298982 GA/AA genotypes had a 50% increased risk of ovarian endometriosis in the parity≤1 subgroup, suggesting that the biological function of METTL14 gene might impact the risk of infertility." (PMID 39831202, 2024).
intracerebral hemorrhage (1 paper, 2026). A cerebrovascular disorder characterized by bleeding into one or both cerebral hemispheres including the basal ganglia and the cerebral cortex. "Furthermore, the protein abundance of METTL3 was also higher and that of METTL14 was lower in mice with collagenase-induced intracerebral hemorrhage than in controls." (PMID 41601663, 2026).
ischemia (1 paper, 2022). A hypoperfusion of the BLOOD through an organ or tissue caused by a PATHOLOGIC CONSTRICTION or obstruction of its BLOOD VESSELS, or an absence of BLOOD CIRCULATION. "Cardiac-specific METTL14 knockdown attenuates acute ischemia-reperfusion injury as well as cardiac dysfunction in ischemia-reperfusion remodeling." (PMID 36351918, 2022).
juvenile myelomonocytic leukemia (1 paper, 2026). A myelodysplastic/myeloproliferative neoplasm of childhood that is characterized by proliferation principally of the granulocytic and monocytic lineages. "In this study, we found that m6A methyltransferase methyltransferase-like 14 (METTL14) was highly expressed and associated with a shorter survival in a RAS-mutation myeloid malignancy, juvenile myelomonocytic leukemia (JMML)." (PMID 40819104, 2026).
leukopenia (1 paper, 2022). "A reduced frequency of the METTL14 rs62328061 G allele was associated with leukopenia, a reduced frequency of the WTAP rs11752345 T allele was associated with sputum smear positivity, and a higher frequency of the METTL14 rs4834698 TC genotype was evident in PTB patients with hypoproteinemia." (PMID 36569923, 2022).
male infertility (1 paper, 2022). The inability of the male to effect fertilization of an ovum after a specified period of unprotected intercourse. "With germ cell-specific inactivation of Nat10, both Mettl3 and Mettl14 can cause defects in spermatogenesis and male infertility." (PMID 35801907, 2022).
metastatic tumors (1 paper, 2018). "Downregulation of METTL14 showed a worse outcome in HCC patients and METTL14 mRNA expression was found to be further lower in metastatic tumors or portal vein tumor thrombus." (PMID 29374143, 2018).
Miscarriage (1 paper, 2022). A pregnancy that ends at a stage in which the fetus is incapable of surviving on its own, defined as the spontaneous loss of a fetus before the 22th week of pregnancy. "Inhibition of METTL14 expression reduces viability, proliferation, and migration of HTR8 cells, and may serve as a potential novel target for diagnosis and treatment of spontaneous miscarriage." (PMID 36118846, 2022).
Myocardial fibrosis (1 paper, 2024). "Underlining the molecular mechanisms of m6A in participating in myocardial fibrosis and remodeling, it pointed toward novel intervention strategies, including targeting METTL3 and METTL14 in peripheral blood monocytes." (PMID 38948064, 2024).